PEBP1 (phosphatidylethanolamine binding protein 1)
Diseases named in the same sentence as PEBP1 in open-access papers (continued):
Sharing a sentence is not in itself a finding about the gene and the disease.
tumor (continued). "A particularly strong and uniform negative correlation was evidenced between the co-expression of these genes and the transcription of several major matrix metalloproteinase (MMPs) and PEBP1/STK11 levels, indicating a suppressive effect on local tumor invasion." (PMID 40806276, 2025). "The well-established tumor-suppressive functions of RKIP (PEBP1) and LKB1 (STK11) suggest that their expression, either independently or in concert, may influence cancer progression through effects on the tumor microenvironment (TME)." (PMID 40806276, 2025). "Understanding how PEBP1/STK11 co-expression may interfere with the function and properties of tumor MM is essential for gaining deeper insights into tumor metabolism and its potential therapeutic implications." (PMID 40806276, 2025). "The notable exception of this trend was observed in COAD, READ, and STAD, where CXCR3 displayed a positive correlation with PEBP1/STK11 expression, highlighting the complex and context-dependent interplay between PEBP1/STK11 and chemokine-mediated immune regulation in the tumor microenvironment." (PMID 40806276, 2025). "Importantly, we show that PEBP1 methylation is negatively correlated with its mRNA expression, in pan-cancer, with LUSC, SKCM, LGG, HNSC, and LIHC being the leading tumor entities in this anti-correlation." (PMID 37894300, 2023). "Conversely, the underexpression of genes like PEBP1, NAPSA, and FDX1 in ccRCC may indicate their roles as tumor suppressors or regulators of critical cellular processes." (PMID 37985807, 2023). "The protein level of ferroptosis-related genes was verified by the HPA database and IHC test, leading to the discovery that the expressions of ALOX5, PEBP1, ACSL4, and ZEB1 proteins up-regulated in tumor tissues, and existed differences between tumor tissues and normal tissues." (PMID 36313708, 2022). "Our results are therefore unlikely to be explained by an intrinsic effect of PEBP1 on tumor cells or their metastatic counterparts." (PMID 28978044, 2017). "Note, two of the significantly regulated tumour proteins, i.e. CRK and PEBP1 are members of the EGFR1 signalling pathway with PEBP1 also functioning as a master regulator while the other regulated proteins are connected to EGFR signalling through cross-talk among the pathways." (PMID 25872475, 2015). "In THYM in specific, we found that PEBP1 methylation significantly correlates with infiltration of CD4 T cells, CD4 naïve T cells, CD8 T cells, CD8 naïve T cells, central memory, DC, effector memory, MAIT, macrophages, monocytes, neutrophils, Tfh, Th1, Th2, and nTreg cells in the tumor." (PMID 37894300, 2023). "Low PEBP1 expression led to reduced survival in LUAD, and in vitro experiments demonstrated that upregulation of PEBP1 expression can suppress the proliferation and invasion of LUAD cells, which indicates that PEBP1 may act as a tumor suppressor gene." (PMID 35757748, 2022). "We then explored the methylation levels (beta values) of YY1 and PEBP1 across different TCGA tumors and found that PEBP1 is highly methylated in LGG, LAML, LUAD, LUSC, and HNSC, among other tumors, while YY1 is not significantly methylated in any tumor." (PMID 37894300, 2023). "Based on the molecular context in which we find PEBP1 to be expressed, we postulate that a decrease in PEBP1 may be indicative of a skewing of the (DC-vaccine-triggered) immune response towards chronic inflammation/myeloid immune suppression rather than towards an effective anti-tumor response." (PMID 28978044, 2017).
cancer (141 papers, 2007 to 2026). A tumor composed of atypical neoplastic, often pleomorphic cells that invade other tissues. "Among the hypoxia-related molecules, MRPS17, CDCHD2, PSMA7, and MIF consistently demonstrated a positive correlation with PEBP1/STK11 co-expression across all cancer types in which a significant association was observed." (PMID 40806276, 2025). "An integrated analysis was further conducted to assess the regulatory impact of the PEBP1/STK11 co-expression signature on ten major cancer-associated pathways across diverse cancer types." (PMID 40806276, 2025). "In contrast, CXCL13 was negatively associated with PEBP1/STK11 co-expression in almost all cancer types." (PMID 40806276, 2025). "We constructed a univariate Cox proportional-hazard regression model to predict the prognostic risk of YY1 and PEBP1 in pan-cancer, and found that the two genes associate with the prognoses of various tumors." (PMID 37894300, 2023). "In Homo sapiens, PEBP1 (RKIP) has been implicated in several cancers, probably acting as a metastasis suppressor." (PMID 36430314, 2022). "Loss or reduced expression of PEBP1/RKIP has been reported in aggressive cancer cells such as gastrointestinal tumor." (PMID 29719584, 2018). "In this study, we use a computational, transcriptomics-based pan-cancer approach to explore whether co-expression of PEBP1 and STK11 is associated with distinct TME profiles." (PMID 40806276, 2025). "First, we explored the YY1 and PEBP1 gene mutation rate in pan-cancer." (PMID 37894300, 2023). "Low expression of PEBP1 is associated with cancer metastasis and poor prognosis." (PMID 34885208, 2021). "Additionally, ACOX3, ACAD9, ACAD10, ACOT1, ACOT8, and DECR2 displayed positive associations with PEBP1/STK11 co-expression across various cancer types, highlighting a potential involvement in enhancing fatty acid metabolism in the context of PEBP1/STK11 expression." (PMID 40806276, 2025). "Among these, PEBP1/STK11 co-expression strongly negatively correlates in all cancer types with enzymes that increase the biosynthesis of fatty acids such as members of the ACSL family (ACSL1, ACSL3, ACSL4, ACSL5, and ACSL6)." (PMID 40806276, 2025). "RKIP and LKB1, encoded by PEBP1 and STK11, respectively, have emerged as key regulators of cancer pathophysiology." (PMID 40806276, 2025). "Particularly, ACSL4 exhibited the most predominant negative correlation with PEBP1/STK11 co-expression across multiple cancer types, suggesting an inhibitory role in fatty acid metabolism." (PMID 40806276, 2025). "This negative correlation indicates that the higher expression levels of PEBP1 and STK11 are associated with increased drug sensitivity across various cancer types." (PMID 40806276, 2025). "Most of the immune stimulators analyzed demonstrated a complex, cancer type-dependent expression pattern, suggesting that their correlation with PEBP1/STK11 is influenced by the specific TME of each cancer." (PMID 40806276, 2025). "The results indicate that PEBP1 mRNA levels are strongly associated with suppression of the apoptosis inhibition (22%) and EMT (25%) pathways across the pan-cancer landscape." (PMID 40806276, 2025). "The cancers exhibiting the strongest positive correlations between anti-inflammatory chemokine genes and PEBP1/STK11 co-expression were found in the urinary, respiratory, and endocrine systems." (PMID 40806276, 2025). "Overall survival (OS) and Hazard Ratio (HR) analyses were conducted within a pan-cancer framework to assess the impact and the putative clinical significance of the co-expression of the PEBP1 and STK11 transcripts." (PMID 40806276, 2025). "Specifically, the downregulation of PCYT2 in cancer cells not only decreased PE level but also attenuated the interaction between PEBP1 and PPP2R1A." (PMID 39531326, 2024). "PEBP1 (RKIP) has been shown to be decreased in all kinds of cancers, and its absence is closely bond with cancer metastasis." (PMID 38586328, 2024).
cancer (continued). "To further explore the mechanisms underlying the abnormal mRNA expression of YY1 and PEBP1, we explored the relationship between each gene’s CNV and their mRNA expression levels in pan-cancer." (PMID 37894300, 2023). "Here, we found various correlations between YY1/PEBP1 expression (or methylation) and genomic alterations, such as SNVs and CNVs that exhibited a cancer type-specific pattern." (PMID 37894300, 2023). "Studies have shown that PEBP1 is closely related to the occurrence, metastasis, and prognosis of various cancers." (PMID 37622116, 2023). "We next explored the correlation between YY1/PEBP1 mRNA levels and immune infiltration in pan-cancer." (PMID 37894300, 2023). "Our study further detected several correlations between YY1 and PEBP1 mRNA expression and immune infiltration across different cancers." (PMID 37894300, 2023). "The down-regulated expression of PEBP1 is observed in several human cancers, which has defined it as a metastasis suppressor gene." (PMID 37762371, 2023). "Dysregulation of YY1 and PEBP1 expression patterns has been reported across different types of cancer." (PMID 37894300, 2023). "In H. sapiens, PEBP1 (RKIP) is a metastasis suppressor in aggressive cancers and cell cycle modulator." (PMID 36430314, 2022). "Subsequent studies verified that PEBP1 was downregulated in diverse cancers, which contributed to the malignant biological behavior of cancer cells." (PMID 35840930, 2022). "For instance, studying PEBP1 in cancer showed that it controls the cell cytoskeleton by interacting with actin, as well as regulating various signaling pathways and GTPases upstream of actin cytoskeleton regulation." (PMID 34941772, 2021). "GAP43 and BASP1 have previously showed significant associations with tau concentration, together with for example the cancer-associated protein LY6H, and PEBP1 which is believed to have implications for AD." (PMID 33653397, 2021). "PEBP1 inhibits cancer metastasis at different stages, including epithelial to mesenchymal transition (EMT), migration, and invasion." (PMID 34885208, 2021). "To illustrate the use of the cRegulome package in answering relevant biological questions, we studied candidate transcriptional regulators of RKIP, an anti-cancer gene product known also as phosphatidylethanolamine binding protein (PEBP1)." (PMID 30867986, 2019). "The decreased expression of PEBP1/RKIP has been reported in many types of cancer cells and malignant tissues." (PMID 29719584, 2018). "Several brown module members that correlated strongly with the expression of RKIP/PEBP1 have known functions in cancer development and progression." (PMID 30115852, 2018). "PEBP1 has previously been described to modulate several major cancer and inflammatory signaling pathways." (PMID 28978044, 2017). "We first assessed the percentage of YY1 and PEBP1 (heterozygous and homozygous) CNVs in pan-cancer." (PMID 37894300, 2023). "Finally, we collected the IC50 of various drugs across different cancer cell lines from the GDSC and CTRP databases and associated them with the corresponding YY1 and PEBP1 mRNA levels." (PMID 37894300, 2023). "Additionally, YY1/PEBP1 expression and methylation displayed connections with genomic alterations across different cancer types." (PMID 37894300, 2023). "Serving as a physiological endogenous inhibitor of the RAF1/MEK/ERK pathway, PEBP1 may inhibit cancer cell migration, proliferation, and invasion." (PMID 37985807, 2023). "PEBP1 has been reported in cancers of various tissue origins." (PMID 37371811, 2023). "Downregulation of PEBP1 leads to major diseases, such as cancer and Alzheimer’s disease." (PMID 35736727, 2022). "It has been reported that PEBP1 could serve as a suppressor in cancer progression via the Raf1/MEK/ERK signaling pathway." (PMID 35840930, 2022). "In general, the expression of PEBP1 is found to be much lower in cancer cells, and therefore, its upregulation might limit the metastatic potential." (PMID 34873567, 2021).
cancer (continued). "Compared with normal tissue, PEBP1 is generally underexpressed in most cancers, including HCC." (PMID 34925691, 2021). "Understanding the interactions of RKIP/PEBP1 with these gene products may give insight into its role cancer development." (PMID 30115852, 2018). "Moreover, our epithelial-to-mesenchymal transition (EMT) analysis revealed a consistent inverse association between PEBP1/STK11 co-expression and EMT marker genes, including SNAI1, SNAI2, FOXC2, ZEB1, and FN1, across most cancer types examined, thus underscoring a uniform anti-EMT signature." (PMID 40806276, 2025). "Overall, our findings provide new evidence supporting the hypothesis that high PEBP1/STK11 co-expression may be involved in suppressing EMT-related features of cancer cells within the TME, which opens new avenues for hypothesis-driven research for the remodeling of the TME." (PMID 40806276, 2025). "Among them the Raf kinase inhibitory protein (RKIP), encoded by Phosphatidylethanolamine Binding Protein 1 (PEBP1), has been identified by us and others as a key regulator of intracellular signaling pathways involved in physiological processes and disease pathogeneses, such as cancer." (PMID 40806276, 2025). "On the other hand, OV demonstrated an entirely opposite trend, with strong positive correlations between PEBP1/STK11 co-expression and the majority of glucose metabolism genes, pointing to a unique metabolic signature in this cancer type." (PMID 40806276, 2025). "PEBP1/STK11 co-expression was further shown to modify the mechanical and structural components of the TME across human cancers." (PMID 40806276, 2025). "Taken together, we used multiple prognostic datasets for pan-cancer and preliminarily revealed that the high mRNA levels of YY1 and PEBP1 significantly correlate with a poor prognosis for different cancer patients." (PMID 37894300, 2023). "Overall, the analysis of multiple prognostic datasets pan-cancer revealed the cancers in which YY1 and PEBP1 significantly correlate with a good or bad prognosis, respectively." (PMID 37894300, 2023). "By integrating multiple data sources and applying advanced computational methods, we aimed to identify novel insights into the role of PEBP1/RKIP and YY1 in cancer, as well as potential therapeutic targets and biomarkers." (PMID 37894300, 2023). "PEBP1 regulates activities of several other protein kinases in NF-kB and PI3K/Akt/mTOR pathways to implicate in cancer." (PMID 35736727, 2022). "In conclusion, previous studies have reported that PHKG2, PEBP1 and NCOA4 are positive regulators that promote ferroptosis in some kinds of cancers, whereas the remaining two genes (ACSL3 and CISD1) suppress ferroptosis in cells." (PMID 34115610, 2021). "Multiple module members share a common regulator that contribute to cancer formation, with RKIP/PEBP1." (PMID 30115852, 2018). "Raf kinase inhibitory protein (RKIP), also known as phosphatidylethanolamine binding protein 1 (PEBP1), is a highly conserved protein that is commonly lost or downregulated in cancers." (PMID 30181452, 2018). "In contrast, a uniform negative association with PEBP1/STK11 co-expression was found in most of the genes encoding TNF ligands (ENFSF13B, TNFSF4, TNFSF9, TNFSF14, TNFSF18, and TNFSF15) in almost all cancer types." (PMID 40806276, 2025). "Notably, CHOL and UCS cancers exclusively exhibited negative associations with all glucose metabolism-related genes that significantly correlated with PEBP1/STK11 co-expression, highlighting a distinct metabolic phenotype in these cancer types." (PMID 40806276, 2025). "Nevertheless, in several cancers, hypoxia-related molecules generally showed a negative correlation with the co-expression of PEBP1/STK11, including CHOL, LIHC, PAAD, BLCA, BRCA, UCS, LUAD, and SARC." (PMID 40806276, 2025).
cancer (continued). "Glucose metabolism-related molecules exhibited a complex and heterogenous pattern of correlations with PEBP1/STK11 co-expression, with both positive and negative associations observed across various cancer types." (PMID 40806276, 2025). "Among other genes that encode immune inhibitors, IL10, TGFBR1, and IDO1 exhibited a broadly negative correlation across most cancer types, aligning with the expression pattern of PEBP1/STK11." (PMID 40806276, 2025). "More specifically, HK3 displayed predominantly negative correlations across most cancer types, suggesting a widespread involvement of these enzymes in metabolic pathways influenced by PEBP1/STK11 levels." (PMID 40806276, 2025). "Laminins, key components of the extracellular matrix (ECM), exhibited predominantly negative correlations with PEBP1/STK11 co-expression across most cancer types." (PMID 40806276, 2025). "Genes like PGK1, PFKP, HK2, and LDHA, that are involved in metabolic reprogramming of cancer cells by enhancing glycolysis have a negative correlation with PEBP1/STK11 co-expression." (PMID 40806276, 2025). "ECM proteases generally showed a widespread negative correlation with PEBP1/STK11 co-expression across all cancer types, with the exception of MMP15 and SPG7, which displayed positive correlations in most of the cancers analyzed." (PMID 40806276, 2025). "Collectively, these findings reveal that PCYT2 inhibited the metastasis of CRC through the PCYT2/PEBP1/YAP1 axis, supporting the significance of metabolic pathways in regulation on cancer metastasis, and they shed light on PCYT2 as a potential therapeutic target for CRC metastasis." (PMID 39531326, 2024). "Raf kinase inhibitor protein (RKIP), whose gene is also known as PEBP1, is involved in the pathogenesis of many cancers, where it has been shown to have pleiotropic functional activities, including the control of cellular proliferation, cell survival, EMT and chemo-radio-immuno-resistance." (PMID 35205667, 2022). "In addition, we analyzed the correlation pair-wise (Pearson’s correlation test), between PEBP1 (RKIP) and SNAI1, VIM, CDH1/2, EPCAM, and LAMA1/B1 genes, across the 22 different types of cancer and normal tissues in the TCGA database." (PMID 36230521, 2022). "In this study, we showed that TGFBR1 has a strong inverse correlation with RKIP/PEBP1, suggesting that the elevated expression of RKIP/PEBP1 may decrease TGFBR1 and suppress cancer progression induced by TGFBR1-dependent signaling." (PMID 30115852, 2018). "In the present study, co-expression of PEBP1/STK11 was predominantly negatively correlated with several pro-inflammatory chemokines and immunosuppressive chemokine receptors, while showing positive correlations with anti-inflammatory chemokines in a cancer type dependent manner." (PMID 40806276, 2025). "Similarly, immune-activating chemokine receptor genes tended to show a negative correlation with PEBP1/STK11 co-expression across all cancer types examined." (PMID 40806276, 2025). "The low expression of RKIP/PEBP1 in cancer cells results in transcriptional and post-transcriptional modifications of proteins such as SNAI1 and NF-κB and consequently promotes the process of the epithelial to mesenchymal transition (EMT), which is an early step of cancer metastasis." (PMID 30115852, 2018). "This might be one way by which RKIP/PEBP1 keeps cancer cells in check, and the absence of it promotes EMT." (PMID 30115852, 2018). "The results showed a statistically significant negative correlation between the ESTIMATE score and PEBP1 and STK11 co-expression patterns across the majority of cancer types." (PMID 40806276, 2025). "Our results revealed both positive and inverse correlations between PEBP1/STK11 co-expression and TME-related molecular signatures, which did not align with classical cancer categorizations." (PMID 40806276, 2025).
cancer (continued). "According to an ongoing study from our laboratory, RKIP/PEBP1 might have some effects on TGFB1-induced EMT and cancer metastasis (data not published)." (PMID 30115852, 2018).
infection (9 papers, 2012 to 2022). The state of being infected such as from the introduction of a foreign agent such as serum, vaccine, antigenic substance or organism. "Several genes upregulated in both obesogenic diet groups (Dpt, PGRP-SC2, and Pebp1) have functions relating to immunity or response to infection." (PMID 29141990, 2018).